PGR (progesterone receptor)
Diseases named in the same sentence as PGR in open-access papers (continued):
Sharing a sentence is not in itself a finding about the gene and the disease.
breast cancer (continued). "An extremely fatal subtype of breast cancer is a triple-negative breast cancer (TNBC), characterized by a lack of expression of the estrogen receptor (ER), progesterone receptor (PR) and non-elevated expression of the human epidermal growth factor receptor (HER2)." (PMID 32443890, 2020). "Triple negative breast cancers are ER−, HER2− and progesterone receptor negative (PR−)." (PMID 32257110, 2020). "TNBC tissues do not express estrogen receptor alpha (ERα), progesterone receptor (PR), and epidermal growth factor receptor 2 (HER2/neu); this is why these tumors are immune to hormonal and HER2-targeting therapies commonly used for breast cancer treatment." (PMID 32260128, 2020). "A recent meta-analysis suggested that ER negativity was an independent risk factor for BMs development, and that the triple-negative (ER, PgR and HER-2 negative) breast cancers showed shorter time to BMs development from the diagnosis of the primary tumor, compared to other breast cancer subtypes." (PMID 32759682, 2020). "Unlike other types of breast cancer, growth of TNBC cells are not fueled by estrogen, progesterone and epidermal growth factor since TNBC is negative for estrogen receptor (ER), progesterone receptor (PR), and overexpression of human epidermal growth factor receptor 2 (HER2)." (PMID 31623629, 2019). "There are three types of breast cancer including estrogen receptor (ER) positive cancer, human epidermal growth factor two positive (HER2) cancer as well as triple negative breast cancer (TNBC) which is negative for ER, PR (progesterone receptor), and HER2." (PMID 30769922, 2019). "In breast cancer, HOXA9 and its downstream target BRCA1 are significantly downregulated, which was thought to be critical for the development of breast cancer in patients lacking estrogen receptor/progesterone receptor expression." (PMID 29662084, 2018). "Triple-negative breast cancer (TNBC) is a disease characterized by the lack of estrogen receptor (ER) and progesterone receptor (PgR) expression as well as human epidermal growth factor receptor 2 (HER2) amplification, and accounts for 10–20% of all breast cancers." (PMID 29796167, 2018). "Triple-negative breast cancers (TNBC), an aggressive form of breast cancer that lacks significant expression of the human epidermal growth factor receptor 2 (HER2), estrogen receptor (ER), and progesterone receptor (PR), accounts for approximately 15~20% of invasive breast cancers." (PMID 29980239, 2018). "Triple-negative breast cancer (TNBC) is characterized by the absence of estrogen receptor (ER) and progesterone receptor (PR), as well as no over-expression of human epidermal growth factor receptor 2 (HER2), and is an aggressive subtype comprising 10–20% of breast cancer incidences." (PMID 29142206, 2017). "Triple-negative breast cancer, defined by the lack of expression of estrogen receptorα (ERα) and progesterone receptor (PR) as well as the absence of overexpression and/or gene amplification of HER2, is a unique subtype of breast cancer with limited treatment options and poor prognosis." (PMID 28969050, 2017). "Based on receptor status, breast cancer is categorized into estrogen receptor (ER)-positive type, progesterone receptor (PgR)-positive type, HER2 positive type, and triple-negative type (ER-negative, PgR- negative, HER2-negative) (TNBC)." (PMID 28966724, 2017). "According to the molecular classification, triple-negative breast cancer (TNBC) is defined as an estrogen receptor α (ERα)-negative, progesterone receptor (PR)-negative, and human epidermal growth factor receptor-2 (HER2)-negative disease, which represents 12–17% of all breast cancers." (PMID 28030791, 2017). "Triple-negative breast cancer (TNBC) that do not express estrogen receptor (ER), progesterone receptor (PR) and human epidermal growth factor receptor 2 (HER2) represent an aggressive subgroup of breast cancer with poor prognosis and limited treatment options in the clinic." (PMID 29172759, 2017).
breast cancer (continued). "Breast cancer is the second most common primary tumor responsible for brain metastasis, especially from women with HER2+ and triple negative [TN, estrogen receptor negative (ER−), progesterone receptor negative (PR−), and HER2−] tumors." (PMID 29164052, 2017). "Triple-negative breast cancer (TNBC), which lacks estrogen receptor (ER) and progesterone receptor (PR) expression as well as human epidermal growth factor receptor 2 (HER2) amplification, is one of the most difficult breast cancers to treat because there is no targeted treatment." (PMID 27363012, 2016). "Luminal A breast cancer was defined as positive for ER and negative for HER2 in the CALGGB9344 trial, positive for ER and/or PgR with a low Ki67 labeling index (cut-off of 13%) in the BCRG01 trial, and positive for ER with a low Ki67 labeling index (cut-off of 20%) in the PACS01 trial." (PMID 27631393, 2016). "One was a case of breast cancer (described as moderately aggressive, BRCA negative, estrogen and progesterone receptor positive) in a 38-year-old female participant diagnosed 281 days after the second study injection and subsequently treated with outpatient lumpectomy, radiation and Tamoxifen." (PMID 27846256, 2016). "Almost all patients included in the study group had an estrogen receptor (ER) positive/HER2 negative breast cancer (67.8%), 27 (9.7%) patients had a ER positive/ HER2 positive breast cancer, 14 (5%) had an HER2 positive/ER and PgR negative and 26 (8.2%) had a triple negative breast cancer." (PMID 27323400, 2016). "Triple-negative breast cancer (TNBC) characterized by the absence of estrogen receptor alpha (ER), progesterone receptor (PR) and human epidermal growth factor receptor 2 (HER2) expression, is a basal-like subgroup of breast cancers that accounts for 10–20 % of all breast cancers." (PMID 27286975, 2016). "Our functional study demonstrates that miR-630 significantly suppressed migration, invasion and colony formation in two aggressive breast cancer cell lines 231-luc and BT549 cells, which are negative of estrogen receptor (ER), progesterone receptor (PR) and HER2." (PMID 26595523, 2016). "A new study by Horst and colleagues confirmed that radiation-preceded breast cancer in survivors of childhood cancer is significantly more likely to the aggressive, the so-called triple negative (negative for ER, progesterone receptor, and amplification of HER2) breast cancer." (PMID 27014632, 2016). "Absence of estrogen receptor, progesterone receptor, and HER2/neu makes TNBC insensitive to some of the most effective therapies available for breast cancer treatment including HER2-directed therapy and endocrine therapies urging the need for identification of new molecular targets in TNBC." (PMID 26098771, 2015). "About three quarters of triple-negative breast cancers (TNBCs)—i.e., estrogen receptor (ER)-, progesterone receptor (PR)- and not overexpressing HER2 —express basal markers, so the triple-negative type is frequently taken as a surrogate marker of basal-like breast cancer." (PMID 26107623, 2015). "Triple-negative breast cancer (TNBC), which can be referred to as the tumors that display absence of estrogen receptor (ER) and progesterone receptor (PR) without the overexpression of human epidermal growth factor receptor 2 (HER2), accounts for 15–20% of breast cancer." (PMID 26020519, 2015). "MCF-10A are normal mammary epithelial cells while MCF-7 (estrogen and progesterone receptor positive, HER2 negative) and MDA-MB-231 (estrogen, progesterone, and HER2 receptor negative) cells represent two different breast cancer cell lines with increasing metastatic potential." (PMID 25385001, 2014).
breast cancer (continued). "Thus a small proportion of older women would be expected to have triple negative (ER, progesterone (PgR) and HER2 negative) breast cancers (TNBCs)." (PMID 24999743, 2014). "Furthermore, BRCA1 mutation carriers seem to predominantly develop estrogen and progesterone receptor-negative and HER2-negative (triple-negative) breast cancer." (PMID 24959366, 2014). "Interestingly, P-cadherin is a marker of triple-negative (which means negative for ER, PgR, and HER2) basal-like breast carcinomas, which comprise a heterogeneous group of tumors that accounts for up to 15% of all breast cancer cases." (PMID 25601904, 2014). "AA women tend to be diagnosed with breast cancer at a younger age and with more aggressive types of the disease, such as ER- (estrogen receptor negative) and ER−/PR−/HER2- (estrogen receptor negative, progesterone receptor negative, HER2 expression negative) breast cancer." (PMID 23593120, 2013). "Clinically, TNBCs are defined by their lack of expression of the oestrogen receptor α (ERα), progesterone receptor (PR) and HER2 (ERBB2), are generally of high histological grade, poorly differentiated and more aggressive compared to other subtypes of breast cancer." (PMID 23436775, 2013). "To investigate the inhibitory effect of anthricin on breast cancer cell growth, we first determined cell viability in 2 breast cancer cell lines: MCF7 (estrogen receptor positive) and MDA-MB-231 (estrogen receptor, progesterone receptor, and Her2/Neu receptor negative)." (PMID 23818925, 2013). "We investigated the changes in cellular viability as well as the expression of the ERα-responsive downstream gene, progesterone receptor (PGR), in response to E2 or TAM, with treatments of GE and TSA alone or together in ERα-negative MDA-MB-231 breast cancer cells." (PMID 23379261, 2013). "Although in some cases of human basal-like breast cancer NG2 is reportedly expressed by tumor cells that are triple-negative for estrogen receptor, progesterone receptor, and HER2, we have found that NG2 is not expressed by mammary tumor cells in the MMTV-PyMT mouse." (PMID 22531600, 2012). "In addition, MDA-MB-435S is a triple-negative cell line (estrogen receptor, progesterone receptor and HER2 negative) that belongs to the basal type of breast cancers, and that are typically unresponsive to receptor-targeted treatments." (PMID 21541295, 2011). "Because the progesterone receptor status of our samples was not well defined, we compared the methylation status of ER-negative and HER2/neu-negative breast tumors (double-negative) with breast cancers expressing either ER or HER2/neu." (PMID 18485221, 2008). "Triple-negative (TN) breast cancer, which is defined as being negative for the estrogen receptor (ER), the progesterone receptor (PR), and the human epidermal growth factor receptor 2 (HER-2), represents a subset of breast cancer with different biologic behaviour." (PMID 18947390, 2008). "Triple-negative breast cancer (TNBC) is distinguished by the absence of the estrogen receptor (ER), progesterone receptor (PR), and human epidermal growth factor receptor 2 (HER2), three pivotal receptors that substantially influence the proliferation and dissemination of breast cancer cells." (PMID 41375077, 2025). "Triple-negative breast cancer (TNBC) is a particular clinical subtype characterized by the absence of estrogen receptor (ER), progesterone receptor (PR), and human epidermal growth factor receptor-2 (HER2) proteins receptors, making up ~15% of BC." (PMID 40841364, 2025).
breast cancer (continued). "Triple-negative breast cancer (TNBC), characterized by the absence of estrogen receptor (ER), progesterone receptor (PR), and human epidermal growth factor receptor 2 (HER2) expression, represents approximately 15%–20% of all BC cases." (PMID 38779451, 2024). "Breast cancer can be categorized into three primary subtypes, hormone-receptor-positive (HR+ BC), HER2-positive (HER2+ BC), and triple-negative (TNBC), based on the presence or absence of the estrogen receptor (ER), progesterone receptor (PR), and ERBB2 (commonly known as HER2)." (PMID 39000600, 2024). "Triple-negative breast cancer is a kind of Basal-like BC without the expression of estrogen receptor (ER), HER2, and progesterone receptor (PR)." (PMID 37689738, 2023). "Triple negative breast cancer (TNBC), defined as estrogen receptor (ER)-, progesterone receptor (PgR)-, and human epidermal growth factor receptor 2 (HER2)-negative breast cancer (BC) has poor prognosis compared to other BC subtypes." (PMID 37007114, 2023). "Triple-negative breast cancer (TNBC), defined by the lack of expression of estrogen receptor (ER), progesterone receptor (PR), and absence of overexpression/amplification of human epidermal growth factor receptor 2 (HER2), is the most aggressive and difficult-to-treat subtype of breast cancer." (PMID 37496019, 2023). "TNBC is negative for the estrogen receptor (ER), progesterone receptor (PR), and human epidermal growth factor 2 (HER2), and therefore does not respond to the targeted therapies that have largely explained the improvements in breast cancer outcomes in recent decades." (PMID 36916687, 2023). "A subgroup of BC tumors in which ER, PGR and HER2 are negative, termed triple negative breast cancer (TNBC), accounts for 15–25% of all BC cases." (PMID 36140723, 2022). "In addition, a BRCA1-mutation is associated with the more aggressive molecular phenotype of FBC (e.g., triple receptor–negative, oestrogen receptor (ER) negative, progesterone receptor (PR) negative, and HER2 negative), earlier disease onset, and family history of breast cancer." (PMID 35804947, 2022). "Triple-negative breast cancer (TNBC) is an aggressive subtype of breast cancer (BC), which is characterized by the total absence of human epidermal growth factor receptor 2 (HER2), progesterone receptor (PR), and estrogen receptor (ER) expression." (PMID 35450041, 2022). "Furthermore, we have shown the therapy resistance of the TNBC line MDA-MB-231 over the estrogen- and progesterone receptor-positive line MCF7, although we failed to advance our understanding of differences in sensitivity to chemotherapy among different types of breast cancers." (PMID 33669671, 2021). "However, increased PD-1, PD-L1, and PD-L2 expression were found more on breast cancer patients with higher ages (>40 years), ductal histology, higher grade, positive estrogen receptor (ER) status, negative HER2 status, and positive progesterone receptor (PR) status." (PMID 34319029, 2021). "Amongst those was a group of breast cancers with a high proportion of rearrangement signature 3, characterised by small tandem duplications (<10 kb), and immunohistochemically defined as triple-negative breast cancer (TNBC); i.e., lacking expression of ER, PgR, and HER2." (PMID 33673506, 2021). "Furthermore, among the common breast cancer subtypes, higher pCR rates were observed in ER-negative (ER−), luminal B HER2-negative (HER2−), nonluminal HER2+, and triple-negative (ER−, progesterone receptor [PgR]-negative, and HER2−) disease." (PMID 31953696, 2020). "Considering the phenotype of human breast cancer cells used in this study, a few physiological characteristics of the MDA-MB-231, which are distinctly different from MCF-7, should be considered including the lack of oestrogen receptors and progesterone receptor expressions." (PMID 31804594, 2019).
breast cancer (continued). "Furthermore, we estimated hormonal therapy for positive estrogen receptor (ER+) or positive progesterone receptor (PR+), and specific targeted therapy for positive human epidermal growth factor receptor 2 (HER2+) for breast cancer patients with or without uterine leiomyoma." (PMID 28380432, 2017). "Clinically, breast cancer is grouped into luminal A (LA), luminal B (LB), human epidermal growth factor receptor 2-positive (HER2+), and triple-negative (TN) subtypes according to estrogen receptor (ER), progesterone receptor (PR), and epidermal growth factor receptor ErbB2/HER2 (HER2) expression." (PMID 28938599, 2017). "Based on biochemical markers, three main breast cancer categories are ER+ (estrogen receptor alpha positive), HER2+ (human epidermal growth factor receptor 2 positive), and TNBC (triple-negative breast cancer; estrogen receptor negative, progesterone receptor negative, HER2 negative)." (PMID 28696357, 2017). "The last one shares many features with BC referred to as “Triple negative breast cancer” (TNBC) (ESR-, progesterone receptor negative (PR-), HER2-), which constitutes 10% to 20% of all BCs." (PMID 28467815, 2017). "In addition, women of African ancestry are at greater risk of having estrogen receptor negative (ER-) and triple negative (ER-, progesterone receptor negative, PR-; and human epidermal growth factor receptor 2 negative, HER2-) breast cancer at all ages compared with European American women." (PMID 27708667, 2016). "We obtained breast cancer tissue from a 44 year old premenopausal female with infiltrative ductal carcinoma (IDC) with ductal carcinoma in situ (DCIS), stage pT1c pN1, Grade II/III, estrogen receptor (ER) positive, progesterone receptor (PR) positive and Her2 negative." (PMID 25010360, 2014). "Prognosis and treatment of patients with breast carcinoma of no special type (NST) is dependent on a few established parameters, such as tumor size, histological grade, lymph node stage, expression of estrogen receptor, progesterone receptor, and HER-2/neu, and proliferation index." (PMID 25082024, 2014). "Regarding breast cancer, Stoesz and coworkers originally reported heterogeneous expression of NGAL mRNA and protein levels in breast cancer tissue that significantly correlated with other markers of poor prognosis including estrogen and progesterone receptor-negative status and high proliferation." (PMID 19889214, 2009). "Triple-negative breast cancer (TNBC) is a specific type of BC defined by the lack of expression of the estrogen receptor (ER), the progesterone receptor (PR), and human epidermal growth factor receptor type 2 (HER2), accounting for approximately 10–20% of all BC cases." (PMID 40497992, 2025). "Based on the molecular expression patterns of BC cells, BC can be divided into three subtypes, with triple-negative breast cancer (TNBC) lacking expression of estrogen receptor (ER), progesterone receptor (PR), and human epidermal growth factor receptor 2 (HER2) expression." (PMID 38182573, 2024). "Triple-negative breast cancer (TNBC), which is characterized by the lack of expression of estrogen receptor (ER), progesterone receptor (PR), and epidermal growth factor receptor 2 (EGFR2/HER2), represents 10–20% of total BC cases and accounts for approximately 30% of BC-related deaths." (PMID 37964363, 2023). "Moreover, estrogen receptor (ER), progesterone receptor (PR), and HER-2 are the main targets for targeted therapy in breast cancer, and samples/cases that are negative for these three receptors are defined as triple negative breast cancer (TNBC), which comprises about 15% of breast cancer cases." (PMID 34552932, 2021). "However, the relationship between Ki67 LI and the expression of PgR has not yet been examined, and the utility of a combined evaluation method using these 2 factors for the selection of a poor prognosis group from ER-positive/HER2-negative breast cancer patients has not yet been established." (PMID 28532429, 2017).